TP63 (tumor protein p63)
Diseases named in the same sentence as TP63 in open-access papers (continued):
Sharing a sentence is not in itself a finding about the gene and the disease.
cancer (continued). "Compared to the other cancer types, the cancer types of the SC class exhibited considerably higher activity scores and expression levels of TP63." (PMID 35227282, 2022). "In this study, we identify that HOXA10-AS serves as a modular scaffold for TP63 mRNA processing and that such involvement regulates cancer growth." (PMID 35858923, 2022). "Downregulated TP63 expression in HOXA10-AS knockdown cells revealed the potential of the AS-TP63 axis in regulating cancer growth." (PMID 35858923, 2022). "Functional assays showed that ectopic TP63 expression relieved the inhibited SAS cancer cell growth by HOXA10-AS knockdown, indicating the involvement of TP63 in HOXA10-AS regulatory signaling." (PMID 35858923, 2022). "Taken together, the available research indicated that FOXP3, IRF3, CD274, and TP63 play an essential role in cancer, even in GBM." (PMID 35401877, 2022). "Among 30 cancer types, we calculated pairwise correlations between miR-944, TP63, and ΔNp63 (Pearson’s correlation test)." (PMID 36077769, 2022). "While we were most interested in the cancerous squamous epithelial cells, the number of CECs (MUC5B, WFDC2) was larger than that of the cancer cells (TP63, KRT5, CDKN2A)." (PMID 35986392, 2022). "TP63 is a classical marker of squamous differentiation in cancer, and our studies suggest ATF3 induction is associated with TP63 expression in invading endometrial epithelial cells following ARID1A loss." (PMID 34941867, 2021). "HPV integration is most frequently detected in genic regions, most often cancer-related genes, such as oncogenes (e.g., TP63, MYC, ERBB2) or tumor suppressor genes (e.g., BCL2, FANCC, HDAC2, RAD51B, CSMD1) and to a lesser extent in miRNA regions." (PMID 34439243, 2021). "Mechanistically, we find that bromodomain-containing protein 4 (BRD4) recruits Mediators and NF-κB p65 to form SEs at cancer stemness genes such as TP63, MET and FOSL1, in addition to oncogenic transcripts." (PMID 34172737, 2021). "For example, in TPRG1 associated with HNSCC potential oncogene TP63, LPP played the role of cancer cell migration, and CCDC50 was essential for cancer cell survival." (PMID 32455963, 2020). "Amplification of TP63 is prevalent in SCCs, and TP63 expression is used to distinguish SCCs from other cancer subtypes in multiple tissues." (PMID 31144617, 2019). "Remarkably, USP22 knockout had pronounced effects on expression of these important cancer-associated gene sets such as c-Myc, E2F, and selected genes including ALDH1A3, CCNE1/G1, E2F6, HOXA1, MMP9, NFKB2, TP63, TPM4, SET7/9 were validated by qRT–PCR." (PMID 31842906, 2019). "There is evidence that TP63 can promote cell survival and proliferation, and is involved in cancer formation and progression." (PMID 31877723, 2019). "In this study, we discovered a universal comutation relationship between ACTL6A and TP63 across almost 25 cancers (p<0.001, log odds ratio>3)." (PMID 31504061, 2019). "Cancer-related target molecules of TP63 identified by IPA were correlated with the apoptotic process, keratinisation, tissue development, and cell population proliferation." (PMID 31877723, 2019). "Global assessment of the impact of Jnk1/2 ablation on gene expression revealed increased P63 mRNA levels, altered expression of downstream targets of TP63, and changes in genes that are enriched for regulating cancer and cell proliferation." (PMID 31089135, 2019). "TP63 is a well-known tumor suppressor gene that can regulate cell cycle progress and inhibit cancer cell proliferation." (PMID 30283353, 2018). "TP63 is essential for skin development, but plays also a crucial role in cancer biology as well as in skeletal muscle homeostasis." (PMID 30487319, 2018). "To further explore potential cancer-associated gene in 3q, we exclude TCNA of 3q and a focal amplification of 3q28 containing gene TP63 emerged." (PMID 29348864, 2017).
cancer (continued). "Recent studies have demonstrated that TP63 regulates cancer stem cell properties by modulating Shh, NOTCH signaling, and miRNAs, including miR-34, miR-205, miR-200, and miR-181." (PMID 28423539, 2017). "Recent studies have shown that TP63 expression is also regulated by miRNAs in specific cancers, which suppress the proliferation and migration of these cancer cells." (PMID 28423539, 2017). "TP63 gene is rarely mutant in human cancers, which is implying of the epigenetic regulation of TAp63." (PMID 26845172, 2016). "Several lines of evidence also implicate TP63 in multiple aspects of cancer initiation and progression." (PMID 23166821, 2012). "ΔNp63 is an isoform of TP63, which is proto-oncogenic and actively expressed in many cancers." (PMID 40650152, 2025). "However, TP63 has two isoforms (TAp63 and ΔNp63), which often exert opposite functions in cancer biology." (PMID 38509096, 2024). "Notably, TP63 was also listed as the top TF regulating genes that are up-regulated in LUSC compared to normal tissues in BART-Cancer (p-value < 0.001)." (PMID 37150829, 2023). "Analysis of LUSC data available from The Cancer Genome Atlas (TCGA) showed that over 30% of tumors have an amplification of TP63, which is more frequent compared to other cancers profiled in TCGA and is among the most frequently amplified transcription factors in LUSC." (PMID 37150829, 2023). "Additionally, several motifs were found to be specifically disrupted in certain cancer types, such as M2321_1.02 (TP63) in Bone-Osteosarc, M6446_1.02 (RARG) in Breast-AdenoCA, and M5371_1.02 (EGR4) in Lymph-CLL." (PMID 37782656, 2023). "Next, we sought to determine whether there are differences in overall survival between TP63 and Ago2 expression in human cancers." (PMID 35459267, 2022). "TP63 alleles have been associated with susceptibility to different cancer types, but not to CRC (some examples:)." (PMID 35158968, 2022). "We next examined the expression of TP63 in the larger cohort of cancer patients." (PMID 35227282, 2022). "Notably, TP63 suppresses apoptosis, metastasis, and the DNA damage response in cancers and was shown to be a sensitive and specific IHC marker for distinguishing and subclassifying LUAD and/or LUSC." (PMID 33676554, 2021). "Additionally, nsSNPs with a high binding affinity score for the mutant TP63–DNA complex represent elevated stability compared to the native complex and can be utilized to obtain efficient drugs to treat cancers." (PMID 34827731, 2021). "With regards to known cancer drivers, 24 showed alterations, including the oral cell lineage transcription factors TP63 (amplified, 21.94%) and SOX2 (amplified, 20.97%), CDKN2A, CCND1 (amplified, 24.27%), PIK3CA (amplified, 20.97%) and EGFR (amplified, 10.67%)." (PMID 31703248, 2019). "Gene Ontology (GO) analysis showed that downregulated genes (decreased greater than onefold relative to control) upon TP63 or SOX2 silencing were strongly enriched for cellular phenotypes important for cancer biology, including cell-cycle regulation, chromatin binding, and cell proliferation." (PMID 30190462, 2018). "TP63 is a gene primarily related to skin development, metabolism and epithelial homeostasis however, there is compelling evidence that it is also involved in cancer." (PMID 30446632, 2018). "TP63 regulates a subset of miRNAs in multiple human cancers." (PMID 28423539, 2017).
cancer (continued). "Moreover, the upregulation of TP63 expression was also demonstrated in various types of solid malignancies, including cancers of the lung, esophagus, breast, skin, and bladder." (PMID 28423539, 2017). "In this study, we detected high levels of TP63 expression in patients with these carcinomas." (PMID 28258440, 2017). "Notably, it is known that this cancer type frequently harbors amplified TP63." (PMID 33263276, 2020). "Besides, the TP63 gene is rarely mutated in human cancers, indicating that p63is not a canonical tumor suppressor." (PMID 26845172, 2016). "Presently the relationship between this amplification and cancer initiation is unknown, however ΔNp63α is a survival factor that opposes a pro-apoptotic gene expression program suggesting a correlation between TP63 amplification and therapeutic resistance." (PMID 23166821, 2012). "In ESCA, ALDH3A1 is regulated by the core regulatory circuitry transcription factors TP63, SOX2 and KLF5 and is involved in the proliferation of cancer cells." (PMID 40529228, 2025). "Rearrangement of TBL1XR1 (3q26.32) have been identified in various cancers involving different genes, including RARA (17q21), HMGA1 (6p21), TP63 (3q28), RET (10q11.2), and PIK3CA (3q26.32)." (PMID 41123735, 2025). "Transcription factors TP63, SOX2, and KLF5 have been demonstrated to influence chromatin dynamics and contribute to cancer-specific gene ALDH3A1 inactivation in ESCC." (PMID 40523880, 2025). "Red dots denote significantly upregulated genes, such as TP63, NTRK2, and CLCA2, highlighting their elevated expression in cancer samples." (PMID 40370696, 2025). "We also examined other genes whose expressions were modulated by TP63 or LTR12C activation and the viability of the cancer cell lines after treatment." (PMID 40498028, 2025). "The differential expression of the TP63 and YAP1 genes in cervical SCC and ADC suggested that p63 and YAP1 play opposing roles in the progression of these two types of cancer." (PMID 40603978, 2025). "We find that recurrent somatic mutations in conserved enhancer regions largely correspond to those associated with known transcription factors with a role in pancreatic development and cancer, including KLF5 and TP63." (PMID 40971319, 2025). "Subsequently, the LUAD marker genes NAPSA, NKX2-1, the LUSC marker genes TP63, KRT5, as well as EPCAM and MET were adopted to identify the cancer cell clusters." (PMID 38382091, 2024). "We further integrated our methylation results with RNA-seq data, and we identified 11 genes, including six related to immune functions (AHR, LRFN5, NTRK2, RSPO2, SAMSN1, and TFEC), and three related to cancer (SLC12A5, SORCS1, and TP63)." (PMID 39795948, 2024). "Based on the Cancer Genome Atlas (TCGA) cancer database, we used LASSO regression analysis to identify the six prognostic-related genes with both DDR and EMT functions, including TP63, YWHAZ, BRCA1, CCND2, YWHAG, and HIPK2." (PMID 36673982, 2023). "We found that the cancer subtype markers (GRP, CHGB, NEUROD1, and CHGA for NET; KRT5, DSC3, KRT6B, TP63, and KRT6A for SCC; and NKX2-1, KRT7, NAPSA, and MUC1 for ADC) were specifically expressed in the corresponding cancer subtypes." (PMID 35962452, 2022).
cancer (continued). "Surprisingly, we found that many cancer cells from P11 not only coexpressed NKX2-1 and TP63 but also showed high expression of CHGB and UCHL1, which are markers of neuroendocrine cells." (PMID 35962452, 2022). "Downstream of SREBF1, a non-canonical, SCC-specific function is elucidated: SREBF1 cooperates with TP63/KLF5 to regulate hundreds of cis-regulatory elements across the SCC epigenome, which converge on activating cancer-promoting pathways." (PMID 34272396, 2021). "Publicly available expression datasets revealed an upregulation of TP63 and USP28 in cancer samples from cervix, oesophagus, head‐and‐neck or lung SCC compared to non‐transformed samples." (PMID 32128997, 2020). "Microarray analysis revealed that DLEU1 knockdown significantly affects expression of a number of cancer-related genes in OSCC cells, including HAS3, CD44, and TP63, suggesting that DLEU1 regulates HA-CD44 signaling." (PMID 30069008, 2018). "qRT-PCR performed to validate the microarray results showed that expression of a number of cancer-related genes, including HAS3, CD44, TP63, and SMYD2, was decreased by siRNAs targeting DLEU1, while expression of CDH1 was increased by DLEU1 knockdown." (PMID 30069008, 2018). "The second subgraph, which contains the largest number of component nodes, has its 95 nodes anchored to the known cancer proteins CTNNB1, APC, PTEN, TP63, MAPK4, MET, RAC1, and ROS1." (PMID 24516372, 2014). "In certain cancer types, like esophageal carcinoma and oral cancer, HOXA10-AS can induce cancer cell proliferation and metastasis by either stabilizing its neighboring gene HOXA10 or serving as a modular scaffold for the processing of TP63 mRNA." (PMID 41425708, 2025). "Moreover, the co-activation of the super-enhancer-driven CCAT1 by TP63 and SOX2 has been found to promote squamous cancer progression, revealing the interplay between these TFs in cancer." (PMID 41323280, 2025). "TP63 and IGF1 were also involved in some cancer-related pathways." (PMID 39157347, 2024). "Moreover, the recurrent HPV integration analysis at the TAD level revealed both the direct and long‐range effect of HPV integration on the expression of cancer‐related genes (such as MYC, PVT1, TP63 and ERBB2)." (PMID 38013620, 2024). "However, no study has yet looked at the involvement or otherwise of the TP63 and CCR5 genes in the occurrence of cancer in Burkina Faso." (PMID 38585642, 2024). "Additionally, previous studies reported that ESCC-associated proteins, including PCNA, SLC7A5, CTTN, RB1, EGFR, TP63, and PRMT1, exhibited increased expression in S-III; among these proteins, SLC7A5 and EGFR were FDA-approved drug targets for cancer treatment." (PMID 38652547, 2024). "For example, GATA6 expression marks the classical type and is suppressed in the basal type, and a TP63 isoform called deltaN-P63 is suppressed in the classical PDAC transcriptional program and could mark a subset of basal-like cancer cells." (PMID 37124496, 2023).
cancer (continued). "While expression of ACTA2 – a marker expressed by both myoepithelial cells and cancer-associated fibroblasts (CAFs) – significantly increased in CAS compared to normal stroma, expression of TP63, CHD3, MYH11, SERPINB5 and MME did not increase." (PMID 37391533, 2023). "Similarly, the cancer-subtype-specific SEs are densely bound up with its specific master TFs TP63 in ESCC, which participates in the formation of CRC and promotes cancer cell proliferation via PI3K/AKT signaling pathways." (PMID 36387198, 2022). "In TCGA-BRCA, the expression level of miR-944 in cancer tissues was significantly lower than that in non-cancer tissues, and was significantly correlated with ΔNp63 and TAp63 expression, but not with TP63 CNV." (PMID 36077769, 2022). "TP63 c.1459C>T (p.R487C) was found in a man diagnosed with five CRCs and 11–20 adenomatous polyps at age 39, with no familial cancer history." (PMID 35158968, 2022). "TP63 was identified as a differentially expressed gene (DEG) in cancer cell lines that acquired gefitinib resistance, and CSTA is one of the top 10 hub genes in a network of DEGs for gefitinib resistant cancer cell line." (PMID 35584089, 2022). "Key cancer-related transcripts were identified, such as CLDN1, TP63, FGF14, DDX60 and DRAM." (PMID 32839509, 2020). "Over-expression of TP63 may serve as a biomarker predicting the outcome of SCC patients treated with ICB therapy, and targeting TP63/STAT/IFNγ axis may enhance the efficacy of ICB therapy for this deadly cancer." (PMID 38509096, 2024). "Interestingly, our study also revealed hub genes (MEG3, MIAT, IRF1, ADAMTS9-AS2, TP63, NOD2, NOD1, NLRP3, MAGI2-AS3, and PVT1, respectively) within the pyroptosis-related ceRNA network, some of which have been well-studied in the field of cancer biology." (PMID 37511974, 2023). "Notably, in cancers with significantly upregulated miR-944 (BLCA, HNSC, and LUSC), the expression level of miR-944 was at Q4, higher than that of most miRNAs, and miR-944 expression was positively correlated with TP63 CNV." (PMID 36077769, 2022). "Hybrid EMT cells will express epithelial transcription factors such as TP63 or SOX2, and mesenchymal ones, such as SNAIL/SLUG, ZEB1/2 or TWIST1/2, in a way where the expression of genes required for migration or growth can switch on demand depending on the cancer cell’s needs." (PMID 35159370, 2022). "In addition, the regulatory relationship between TP63 and SREBF1 is unknown, and how SREBF1 is epigenetically activated in cancer in general remains unclear." (PMID 34272396, 2021). "Moreover, we find that SREBF1 cooperates with TP63/KLF5 to regulate hundreds of cis-regulatory elements across the SCC-specific epigenome, which converges on activating cancer-promoting pathways, uncovering SREBF1 as a potential therapeutic target and prognostic marker in SCC." (PMID 34272396, 2021). "Therefore, the fact that depletion of STAT6 impaired TP63 upregulation suggests that a STAT6-TP63 axis may be involved, at least in part, in IL-13-mediated suppression of cancer cell migration, extravasation, and eventually metastasis." (PMID 26208975, 2015). "The remaining signaling pathways, which have not been associated with any type of cancer, may exert potential functions in DLBCL; for example, in the present study, hsa-miR-92a-1 was found to target TP63." (PMID 25289101, 2014). "The three ESCC tumors contained an overwhelming majority of cancer cells with notable TP63/SOX2 over-amplification, which was not apparent in EAC cancer cells." (PMID 35785171, 2022).